IL2 (interleukin 2)
Diseases named in the same sentence as IL2 in open-access papers (continued):
Sharing a sentence is not in itself a finding about the gene and the disease.
COVID-19 (continued). "When analyzing by disease severity, IL-2 and IFN-γ levels were higher in severe COVID-19 patients, indicating strong T-cell activation and a heightened immune response, while IL-10 was marginally higher in mild cases, suggesting a protective anti-inflammatory response." (PMID 40557167, 2025). "The cytokine storms are characterized by significant induction of specific cytokines such as IL-6, IL-2, IL-7, GM-CSF, and IFN-γ in COVID-19 patients, which are different from other respiratory viruses with the increase in cytokines such as IL-2, IL-10, IL-4, or IL-5." (PMID 41002992, 2025). "Although most of the components of cellular response and cytotoxicity that we examined were studied after COVID-19 vaccination in the general population (NRF2, TRAIL, LT-α, Fas), only some were studied in people with AIIRD (IL-2, TNF, perforin, granzymes, FasL)." (PMID 40226625, 2025). "Similarly, regarding inflammatory cytokines, high levels of several cytokines, such as IL-1β, IL-2, IL-6, IL-7, IL-8, IL-10, CXCL10/IP-10, MCP-1, and TNF-α have already been described according to the severity of COVID-19." (PMID 39861879, 2025). "Another pathological pathway is represented by the dysregulation of the immune system and, because of the activation of endothelial cells and macrophages, a hyperinflammatory phase appears during COVID-19 with the enormous release of TNF-α, IL-1, IL-2, IL-6, IL-8, and chemokines." (PMID 38999316, 2024). "Considering the vital role of the TLR4–NF-κB signaling pathway in mediating the synergistic stimulation of spike protein and IL-2 in inducing inflammatory cytokines, this pathway presents a promising target for preventing or reducing CRS in patients with COVID-19." (PMID 39359733, 2024). "Although not significant, IFN-γ and IL-2 responses in acute COVID-19 patients showed an increase with severity." (PMID 38212416, 2024). "Plasma levels of IL-2, IL-7, IL-10, granulocyte colony-stimulating factor (G-CSF), IP-10, MCP1, macrophage inflammatory protein 1α (MIP1α), and tumor necrosis factor (TNF) have been observed in patients with severe COVID-19 were higher than in healthy adults." (PMID 38648205, 2024). "The children with MISC_A had higher CD4+IL-2+/million CD3+ values (p-value: 0.03) compared to convalescent COVID-19, higher CD8+IL-2+/million CD3+ (p-value: 0.05) compared to healthy controls, and higher CD4−CD8−IL-2+/million CD3+ median (IQR) values compared to MISC_C (p-value: 0.03)." (PMID 39594853, 2024). "In a recent study, DPSCs cultured with activated T lymphocytes from patients infected with COVID-19 decreased the secretion of several proinflammatory cytokines, including interferon γ (IFN-γ), TNF-α, IL-2, IL-5, IL-9, IL-12 (p70), IL-17A, IL-18, IL-21, IL-23, and IL-2." (PMID 38396665, 2024). "Plasma levels of IL-2, TNF-α, and IL-4 are elevated during the acute phase of COVID-19." (PMID 39188722, 2024). "Pro-inflammatory cytokines such as interleukins IL-2, IL-6, tumor necrosis factor-alpha (TNF-α), interferon-gamma (IFN-γ), and many other molecules, including chemokines, play a significant role in the pathophysiology of COVID-19." (PMID 38707035, 2024). "When COVID-19 patients were categorized into recovered versus long-COVID-19 subgroups, we observed that IFN-γ (P<0.01), IP-10 (P<0.01), IL-8 (P<0.05), and IL-2 (P<0.01) S protein-specific levels were significantly higher in both subgroups compared to unexposed individuals." (PMID 37018291, 2023). "Several proinflammatory cytokines such as tumor necrosis factor-alpha (TNF-α), interleukin (IL)-6, IL-2, IL-7, and IL-10 are involved in the development of cytokine release syndrome (CRS), which then contributes to the high morbidity and mortality of COVID-19 including ARDS." (PMID 37047115, 2023).
COVID-19 (continued). "Therefore, to extend the support for the physiological relevance and anti-inflammatory nature of the identified IL2-AIS, we examined the signature in a well-established inflammatory context in COVID-19 patients, using the COMBAT and INCOV datasets." (PMID 37700317, 2023). "Furthermore, in COVID-19 recovered patients, CD4+ T cells producing high levels of IFN-γ and IL-2 displayed polyfunctional phenotypes that stimulated long-lasting memory T and B cell populations." (PMID 37334376, 2023). "Similarly, elevated levels of IL-6, IL-10, IL-2 and IFN-γ were found in patients with severe COVID-19 due to respiratory failure." (PMID 37917760, 2023). "This inverted expression of the IL2-AIS was specifically observed in COVID-19 patients, but not in the context of other severe pro-inflammatory conditions such as in hospitalised influenza or sepsis patients." (PMID 37700317, 2023). "Our cellular immunity results show that, while HD patients and HV individuals secrete comparable levels of IFN-γ and IL-2 in ex vivo stimulated whole blood at V2+3M in both naïve and COVID-19-recovered individuals, HD patients secrete higher levels of IFN-γ and IL-2 than HV at V3+3M." (PMID 37111331, 2023). "Among the cytokines analyzed in response to S-peptide, some of them such as TNFα, IL-6, IL-2, IFNγ, or CXCL10 were differentially produced between naïve subjects and subjects recovered from COVID-19 early after the second vaccination dose (sample 2), with higher levels in the former group." (PMID 37153580, 2023). "Moreover, inefficient functionality of the overall CD8+ T-cell response, characterized by the low percentage of interferon-gamma (IFNγ+) CD8+ T cells, CD107a+ CD8+ T cells, IL-2+ CD8+ T cells, and granzyme B+ CD8+ T cells, was also detected in COVID-19 cases." (PMID 36839573, 2023). "The levels of Nrf2, HO-1, NFκB, and IL-6 were higher in the granulocytes of COVID-19 patients who died within a week, while the activity of cytoplasmic Cu,Zn-SOD and mitochondrial Mn-SOD and IL-2/IL-10 were lower in comparison to the levels observed in survivors." (PMID 37686388, 2023). "Cytokine content increased in healthy-pregnant subject-EVs compared to non-pregnant EVs, while IL-2 and IL-6 levels were decreased in COVID-19-pregnant subject-EVs compared to healthy-pregnant subject-EVs (p = 0.043, p = 0.0390, respectively)." (PMID 37560162, 2023). "However, HD patients with COVID-19 symptom worsening showed up-regulation (more than 2.5-fold increase) of GM-CSF, IFN-γ, IL-1β, IL-2, IL-6, IL-17A and IL-21, and down-regulation of TNF-α and IL-8 serum levels after the dialysis procedure." (PMID 36675231, 2023). "The ongoing inflammatory response after acute COVID-19 remission keeps the expression of proinflammatory cytokines such as IFN-β, IFN-λ1, IFN-γ, IL-2, IL-6, IL-17, CXCL8, CXCL9, and CXC10 upregulated, the activation of non-classical and intermediate monocytes, fibroblasts, and myeloid cells." (PMID 38097988, 2023). "Acute COVID-19 children had significantly elevated levels of cytokines, (Interferon (IFN)) IFNγ, Interleukins (IL)-2, TNFα, IL-1α, IL-1β, IFNα, IFNβ, IL-6, IL-12, IL-17A and Granulocyte-Colony Stimulating Factors (G-CSF) in comparison to convalescent COVID-19 and controls." (PMID 37013538, 2023). "Interestingly, the severely infected patients with COVID-19 were reported to have CD4+ T cells secreting lower levels of IFN-γ, IL-2, and TNF-α as compared to the patients with mild symptoms." (PMID 36679947, 2023). "In all three datasets analysed, we found that the IL2-AIS score was not correlated with age or sex, although both factors were found to be associated with COVID-19 severity and PASC symptoms." (PMID 37700317, 2023). "Enrichment of IL-20, IL-2, IL-6, KIT, and JAK-STAT signaling pathways was unique to monocytes and DCs from patients with COVID-19, suggesting that innate immune cells may be much more active and cytotoxic in COVID-19 compared to in HIV-1." (PMID 36992700, 2023).
COVID-19 (continued). "S17 and S18, respectively) showed potential trends toward increasing spike-specific CD8+ T cell degranulation response (CD107a+), higher frequencies of spike-specific CD4+ IL-2+ T cells, and higher frequencies of spike-specific CD4+ IFN-γ+ T cells in COVID-19 convalescent patients (P = 0.036)." (PMID 37824612, 2023). "Overall, IL-2 secretion in response to spike, membrane or nucleocapsid peptide stimulation was not different as measured by Kruskal-Wallis ANOVA (p>0.999) between the Long COVID seropositive group and the D180 COVID-19 confirmed positive group." (PMID 35772216, 2022). "In the non-survivor COVID-19 patients, patients’ age, D-dimer, and creatinine kinase were significantly higher, and IL-1 β, IL-2, and IL-8 were significantly lower compared with the levels in the survivors." (PMID 36294868, 2022). "IL-2 expression behaved in the same way as observed in cell percentage, displaying a significant 2-fold diminution in helper T cells from participants that after SARS-CoV-2 infection developed severe COVID-19 compared to the mild disease group (P = 0.0075)." (PMID 35860236, 2022). "The cytokine storm has already been attenuated following recovery from COVID-19, as levels of TNF-α, free active TGF-β, IFN-γ, IL-1β, IL-2, IL-4, IL-6, IL-8, IL-10, IL-12p70, IL-17 and MCP-1/CCL2 during convalescence were not higher compared to healthy volunteers." (PMID 35757700, 2022). "Moreover, COVID-19 patients were reported to have reduced NK cell functional markers such as CD107a+ (a degranulation marker), granzyme B, IFN-γ+, IL-2+, and TNF-α+ compared to healthy controls." (PMID 35273641, 2022). "We then investigated CD4+, Treg and CD8+ T cells polyfunctionality by analyzing simultaneous production of TNF-α, CD107a, IFN-γ, IL-2, IL-17, granzyme-B and TGF-β by mild, moderate and severe COVID-19 convalescent patients at recovery time-point I and time-point II, as well as by healthy donors." (PMID 35757700, 2022). "Furthermore, of the 12 patients in our cohort who were hospitalised with COVID-19, 100% (12/12) were positive for SARS-CoV-2 IL-2 T cell responses while only 50% (6/12) were antibody seropositive." (PMID 35772216, 2022). "In addition, cytokines in COVID-19 patients, including IFN-γ, IL-2, and IL-4 were observed to decrease compared to levels in HCs." (PMID 35422810, 2022). "We found that acute COVID-19 neutrophils secreted reduced G-CSF, MIP-1α, MIP-1β, MCP-1, IL-2, SDF-1α, IL-9, IL-17A, IL-18, IL-20 and IL-23 levels, but secreted increased soluble PD1, IP-10 and MIP-2α levels compared to rec-phase and healthy neutrophils upon bacterial challenge." (PMID 35007290, 2022). "These previous studies have analyzed T –cell immunity to COVID-19 mRNA vaccination in patients with hematological malignancies by intracellular cytokine staining and flow cytometry, or by measurement of secreted IFN-γ/IL-2 by ELISpot or FluoroSpot techniques." (PMID 36703960, 2022). "During the development of COVID-19, SARS-CoV-2 infection induced an excessive immune response and released a variety of pro-inflammatory cytokines through the JAK/STAT pathway, such as IL-2, IL-6, and granulocyte colony-stimulating factor signaling." (PMID 35721149, 2022). "The data obtained show that mothers affected by COVID-19 have an increase in pro-inflammatory factors (TNF-α, TGF-β, IL-2, IL-6, IL-8) compared to controls; this increase could generate a sort of “protection of the fetus” from virus attacks." (PMID 35408809, 2022). "High levels of proinflammatory cytokines interleukin 2 (IL-2), IL-6 and IFN-γ were detected in sera of patients with severe COVID-19, suggesting that SARS-CoV-2 may usurp JAK-STAT signaling for pathogenesis." (PMID 35317858, 2022).
COVID-19 (continued). "While baseline secretion of proinflammatory cytokines was massively elevated, whole blood from COVID-19 patients elicited diminished release of T-cellular (e.g., IFN-γ, IL-2) and innate immune cell-derived (e.g., CXCL9, CXCL10) cytokines in response to A. fumigatus and R. arrhizus antigens." (PMID 36052094, 2022). "We included in our tests a set of cytokines and chemokines with serum concentrations that were shown to increase during COVID-19, and this increase might also be reflected in breastmilk: TNF-α, IL-6, IFN-β, IL-1β, IFN-γ, IL-2, GM-CSF and IL-5, IP-10." (PMID 36560410, 2022). "This notion might partially explain why participants that showed helper and cytotoxic T cells with increased PD-1 expression and decreased IL-2 and IFN-gamma production in response to polyclonal stimuli tended to develop severe COVID-19 once infected." (PMID 35860236, 2022). "This supported the conclusion that CoVPSA might be a relevant antigen to incorporate in COVID-19 vaccines to induce high levels of anti-viral cytokines, such as IFN-γ, IL-17A, and IL-2." (PMID 35440789, 2022). "Regarding the cytokine profile of S-specific T-cells, post-COVID-19 patients with pneumonia and vaccinated subjects produced similar levels of TH1 cytokines, in particular IFNγ, IL-2, TNFα, and MIP-1β, which were significantly higher than in post-COVID-19 patients with mild symptoms." (PMID 35744768, 2022). "Therefore, we analyzed the viral loads and the differential gene expression profiles of eight cytokines (IL-1, IL-2, IL-4, IL-6, IL-10 IFN-γ, TNF-α, and TGF-β1) in a total of 118 qPCR confirmed COVID-19 cases." (PMID 36584119, 2022). "Previous reports on immune response to SARS-CoV-2 have shown that T cell response is greatly diverse, as T cells from COVID-19 patients can secrete TH1 cytokines, including IFN-γ and TNF, TH17 cytokines, including IL-17A, TH2 cytokines, including IL-4, and others, including IL-2 and CD107a." (PMID 35386702, 2022). "TNF-, IL-2, IL-6, IL1B, IL7, IL10, IFN-, GCSF, CXCL10, CCL2, ferritin, D-dimer, fibrinogen, leukocytosis, and C-reactive protein (CRP) levels are significantly higher in critically ill COVID-19 patients." (PMID 35645351, 2022). "This decreased expression of certain cytokines (IL-2, IL-6, TNF-α, and IFN-γ) in the nasopharyngeal milieu may be considered early biomarkers for disease severity in COVID-19 patients." (PMID 36584119, 2022). "The cytokine profile obtained was adequate because it mainly involved anti-viral cytokines IL-12, IL-17A, and IL-2, not cytokines participating in the COVID-19 cytokine storm, such as IL-6 or IL-10." (PMID 35440789, 2022). "Non-pregnant patients with severe COVID-19 have been found to have greater levels of IL-2, IL-6, IL-7, IL-10, IP-10, MCP-1, TNF-α, macrophage inflammatory protein 1 alpha, and granulocyte-CSF than those with mild and moderate infections." (PMID 36383608, 2022). "Additionally, IL-4, IL-12, IL-2, CXCL10, platelet derived growth factor subunit A (PDGFA), and IFN-α2a kinetic changes were similar between the natural course of early COVID-19 and inhaled budesonide." (PMID 35397798, 2022). "In the post-COVID-19 group, subjects with long COVID-19 had higher levels of IL-17 and IL-2 (p<0.05), and subjects without sequelae had higher levels of IL-10, IL-6 and IL- 4 (p<0.05)." (PMID 35846757, 2022). "We investigated the circulating levels of the G-CSF, GM-CSF, M-CSF, IL-3, IL-7, FLT3L and IL-2 growth factors and soluble receptor sIL2Ra in the surviving and non-surviving severe COVID-19 patients and healthy controls." (PMID 36142255, 2022). "According to the results of cytoscape, the targets of JFBDS for treating COVID-19 mainly contained EGFR, PIK3CA, lymphocyte-specific protein tyrosine kinase (LCK), mitogen-activated protein kinase 1 (MAPK1), MAPK3, MAPK8, STAT3, TNF, IL2 and RELA." (PMID 35165507, 2022).
COVID-19 (continued). "In addition, it was also found that the plasma levels of IL2, IL7, IL10, IL-6, TNFα, and e lymphopenia were higher in patients with COVID-19." (PMID 35295802, 2022). "Moreover, COVID-19 patients who were admitted had a substantial accumulation of inflammatory cytokines, including TNF-а, IL-6, IL-2, and IL-10, especially in severe COVID-19." (PMID 35573725, 2022). "Cytokine storm of interleukin (IL)-2, IL-4, tumor necrosis factor-alpha (TNF-α), interferon-gamma (IFN-γ), and C-reactive protein has not been directly associated with COVID-19, whereas IL-6 and IL-10 were found to be COVID-19 severity predictors." (PMID 35054524, 2022). "Functional clusters identified among Treg cells showed high proportion of cells with simultaneous production of different combinations of TNF-α, IL-2, CD107a, and IFN-γ (which have been found before in the entire population of CD4+ cells) at time-point I in severe post-COVID-19 patients." (PMID 35757700, 2022). "Higher levels of IL-2, IL-10, IFN-γ, and MCP-1 are indicators of mild COVID-19." (PMID 36561720, 2022). "Furthermore, the expression of CD94/NK group 2 member A (NKG2A) was increased on cytotoxic T lymphocytes (CTLs) and NK cells in COVID-19 patients, accompanied by low levels of CD107a, IFN-γ, IL-2, TNF-α, and granzyme B." (PMID 33987176, 2021). "Our results showed 13 potential targets of biochanin A; the molecular interaction network analysis using Cytoscape further highlighted the involvement of six core targets of biochanin A, EGFR, CCND1, IL2, IL1A, IL6R, and PPARG, for the treatment of CRC/COVID-19." (PMID 34931923, 2021). "Interestingly, in wave 2, only IL-1ra, IL-2, IL-6 IL-8 and IFN-γ concentrations were significantly higher in serum of mild and severe COVID-19 patients compared to controls." (PMID 34675240, 2021). "In a recent study we showed that COVID-19 patients generate a large number of polyfunctional antigen-specific T cells, expressing at least two of the pro-inflammatory Th1 cytokines TNF, IL-2, IFNγ or the cytotoxic granzyme B, after stimulation with M, N or S OPPs." (PMID 34228322, 2021). "In patients with COVID-19 hospitalized due to hypoxemia, IL-2 appears at higher levels although studies did not demonstrate a direct correlation with a worse outcome." (PMID 34336904, 2021). "The possible increase of IL-2, IL-12, TNF-α, and interferon (IFN)-γ levels after mRNA COVID-19 vaccination might be the rationale for new onset psoriasis and flares after mRNA COVID-19 vaccine administration." (PMID 34945136, 2021). "Indeed, the plasma levels of interleukin-2 (IL2), interleukin-6 (IL-6), tumor necrosis factor α (TNFα), and C-reactive protein (CRP) are markedly elevated in COVID-19 patients." (PMID 34326911, 2021). "Of note, a recent study has shown that the magnitude of T cell responses to SARS-CoV-2 was similar between asymptomatic infections and symptomatic COVID-19 patients, but SARS-CoV-2-specific T cells produced a higher level of IFN-γ and IL-2 in asymptomatic patient, which is in line with our study." (PMID 34531370, 2021). "In addition, COVID-19 group showed increased TNF-α level and decreased IL-2, IL-6, IL-10, and IFN-γ levels." (PMID 34667157, 2021). "Our data suggested that antigen peptide pools stimulated-IL-2 and -IFN-γ responses could distinguish COVID-19 convalescent individuals from healthy donors." (PMID 34234102, 2021). "Notably, the levels proinflammatory cytokines such as IL-1β, IL-17A, IL-2, and RANTES remained elevated in COVID-19 patients at the early convalescent phase, particularly in those with prior cardiovascular risk, compared to healthy controls." (PMID 33752798, 2021). "To determine whether SARS-CoV-2-specific T-cell immunity was generated and sustained in COVID-19 convalescent patients, we utilized ELISpot assay to measure the number of IFN-γ- and IL-2-secreting T cells, respectively." (PMID 35310397, 2021).